OCRL (OCRL inositol polyphosphate-5-phosphatase)
Diseases named in the same sentence as OCRL in open-access papers (continued):
Sharing a sentence is not in itself a finding about the gene and the disease.
Lowe syndrome (continued). "Studies on Lowe syndrome have suggested that OCRL may act through regulation of TRPV4, and a novel disease-causing OCRL allele prevents TRPV4-mediated calcium signaling." (PMID 38903773, 2024). "Lowe syndrome (OMIM # 309000) is an extremely rare and severe X-linked oculo-cerebro-renal disorder that results from pathogenic variants in the OCRL gene encoding inositol polyphosphate 5-phosphatase OCRL-1." (PMID 38292052, 2023). "To confirm the clinical diagnosis of Lowe syndrome, we analyzed the OCRL gene." (PMID 34488756, 2021). "Lack of complete OCRL expression has been shown previously in several Lowe syndrome patients, and genomic nonsense and frame shift mutations leading to early premature stop codons have been identified in Lowe syndrome and Dent II disease patients." (PMID 34069732, 2021). "Exon duplication of OCRL was found in Lowe syndrome in our previous work." (PMID 33781268, 2021). "We identified four variants of the OCRL gene in four patients with Lowe syndrome, including two novel missense mutations, one recurrent nonsense mutation and a microdeletion encompassing OCRL and SMARCA1 gene." (PMID 31376231, 2019). "It is not yet understood why some OCRL mutations cause the phenotype of Lowe syndrome, while others develop the milder phenotype of Dent-2 disease." (PMID 29300302, 2018). "Upon immunofluorescence staining with OCRL specific antibodies and anti-Arl13b (a small GTPase) antibodies, a marked decrease in OCRL signal was noted in the trabecular meshwork of the Lowe syndrome patient tissue, as compared to the normal human cadaveric control eye." (PMID 28473699, 2017). "It has remained an open question whether individual cell and tissue level pathologies in Lowe Syndrome emerge from defects at specific cellular locations, or from a combination of OCRL-dependent functions." (PMID 29028801, 2017). "Based on our two patients and a literature review, the genotype–phenotype correlation of OCRL mutations with this severe phenotype of Lowe syndrome suggest a possible clustering of missense, deletion, and nonsense mutations in the 5-phosphatase domain and Rho-GAP domain in the Chinese population." (PMID 34488756, 2021). "Thus, knocking out OCRL is a feasible approach to model Lowe syndrome." (PMID 34069732, 2021). "The functional significance of these observations is unclear given that Lowe syndrome does not present with typical Hedgehog loss-of-function phenotypes and that OCRL mutant or KO cells have not been shown to exhibit a defective Hedgehog transcriptional response." (PMID 32970140, 2020). "Similarly, in our study, the patient harboring the interstitial deletion encompassing OCRL and SMARCA1 gene presented with severe features of Lowe syndrome after birth and died at 7 months of age from unknown causes." (PMID 31376231, 2019). "Regarding the OCRL gene, a genotype–phenotype correlation is hypothesized because nearly all truncating variants associated with DD2 are located in exons 1–7, which encompass the PH domain, while variants associated with Lowe syndrome are located in exons 8–24." (PMID 39794284, 2025). "However, human Lowe syndrome model systems are currently limited to static 2D cell cultures of proximal tubule cells or skin fibroblasts isolated from Lowe syndrome patients or kidney-derived cell lines using knockdown or knockout technologies to impair OCRL expression." (PMID 34069732, 2021). "This is the first report of an interstitial deletion encompassing OCRL and SMARCA1 gene in Lowe syndrome." (PMID 31376231, 2019). "Here, we identified an interstitial deletion encompassing the OCRL and SMARCA1 gene in an affected male with severe features of Lowe syndrome." (PMID 31376231, 2019). "Evidence of differential expression of OCRL and INPP5B in human and mice is also presented that potentially explains the mild phenotype of Lowe syndrome murine models." (PMID 23805271, 2013).
Lowe syndrome (continued). "Even though Lowe syndrome is a monogenic disease, no singular mechanism explains the clinical phenotype, likely reflecting the presence of the OCRL gene product Ocrl1 in many tissues with variable expression, subcellular location and complex functions." (PMID 41278199, 2025). "Further, OCRL knockout mice, mutant iPSC-derived iN cells derived from OCRL knockout mice, and the IOB Lowe syndrome mouse model showed a decrease in the activity of the cilia-related sonic hedgehog pathway that organizes the pattern of cellular neuronal differentiation." (PMID 39553960, 2024). "The upregulation of ECM genes, such as collagen in cells lacking OCRL expression, is of interest as interstitial fibrosis has been reported in Lowe syndrome." (PMID 34069732, 2021). "This is in line with previous reports of impaired ciliogenesis in HK-2 cells lacking OCRL and reduced cilia length in dermal fibroblasts isolated from Lowe syndrome patients cultured under static conditions." (PMID 34069732, 2021). "The function of OCRL suggests that the dysregulation of PI4,5P2 levels at endosomes or clathrin-coated vesicles may contribute to the pathological process of Lowe syndrome." (PMID 33061794, 2020). "Our present results demonstrate that the absence of OCRL in Lowe syndrome patient cells results in an impairment of clathrin-mediated endocytosis." (PMID 25107275, 2014). "PTECs lacking OCRL expression exhibited upregulated transcription factor Snai2 and excessive collagen deposition, shedding light on the interstitial fibrosis mechanism in Lowe syndrome." (PMID 38605984, 2024). "Collectively, these data illustrate the possibility that OCRL-related disorders could be rescued by increasing levels of INPP5B, perhaps via AAV gene delivery or via drugs known to upregulate INPP5B expression in Lowe syndrome-affected tissues." (PMID 31413155, 2019). "Defects in clathrin-mediated endocytosis resulting from the lack of OCRL may play a role in the clinical manifestations of Lowe syndrome and Dent's disease." (PMID 25107275, 2014). "Despite the known roles of PHETA1 in facilitating OCRL function, the UDP patient did not present with the typical manifestations of Lowe syndrome, i.e. congenital cataracts, cognitive impairment, and renal tubular and glomerular dysfunction." (PMID 32152089, 2020). "Using this model, we reveal that proximal tubule cells lacking OCRL demonstrate upregulation of epithelial–mesenchymal transition (EMT) marker proteins and increased collagen deposition, which may contribute to interstitial fibrosis as observed in Lowe syndrome patients." (PMID 34069732, 2021).
Dent disease (61 papers, 2009 to 2025). Dent disease is a rare genetic renal tubular disease characterized by manifestations of proximal tubule dysfunction. "Dent disease type 2 (Dent 2), which also results from mutations in the OCRL gene, has similar clinical phenotypes, but they are milder and predominantly involve the kidney." (PMID 41278199, 2025). "In the splicing variant around exon 8, the initiation codon of the OCRL isoform is conserved, leading to Dent disease-2 phenotype." (PMID 40485688, 2025). "Approximately 60% of cases are attributed to pathogenic variants in the CLCN5 gene, which characterize Dent disease type 1 (DD1), while 15% are associated with pathogenic variants in the OCRL gene, defining Dent disease type 2 (DD2)." (PMID 41361832, 2025). "Four patients had causative mutations in the CLCN5, OCRL genes, which are associated with Dent disease, and a heterozygous mutation of the PHEX gene was detected in a patient diagnosed with XLH." (PMID 35612621, 2022). "We present the clinical characteristics of the Asp631Glu mutation in the OCRL gene, presenting as Dent-2 disease with Bartter-like features." (PMID 35549682, 2022). "This rare disorder was characterized by hypercalciuria, low molecular weight (LMW) proteinuria and proximal tubular dysfunction, caused by pathogenic variants in CLCN5 (Dent disease 1) or OCRL (Dent disease 2) genes." (PMID 33430795, 2021). "The second disease-causing gene to be identified as responsible for Dent disease was the OCRL gene (MIM#300535, reference sequence NG_008638.1)." (PMID 32860533, 2021). "Mutations in the OCRL gene cause Dent disease type 2 (DD2), which is identified in about 10–15% of patients with Dent disease." (PMID 32860533, 2021). "About 50%-60% of patients harbor inactivating pathogenic variants of the CLCN5 gene (Dent disease 1), about 15% have the OCRL pathogenic variants (Dent disease 2), and other yet unidentified genes are likely involved in Dent disease." (PMID 33430795, 2021). "The term Dent disease type 2 (MIM #300555) was introduced to distinguish cases with mutations in the OCRL gene from those with CLCN5 mutations (Dent disease type 1)." (PMID 32860533, 2021). "While a role for CLCN5 in Dent disease was suggested in 1994, it was only 11 years later that OCRL was identified as a second disease-causing gene." (PMID 34680992, 2021). "It is becoming increasingly clear that CLCN5 and OCRL gene mutations cannot account for all Dent disease patients." (PMID 32860533, 2021). "In the next sections, we describe the in vitro and in vivo models used to study ClC-5 and OCRL function, and the pathogenic mechanisms behind Dent disease." (PMID 32860533, 2021). "It is also similar to the absence of a severe neurodevelopmental phenotype in a few patients with Dent-2 disease who have apparent null variants in the 5′ end of OCRL." (PMID 30147856, 2018). "Dent disease is a rare X-linked recessive proximal tubulopathy caused by mutations in CLCN5 (Dent-1) or OCRL (Dent-2)." (PMID 27757584, 2017). "To date, approximately 250 families with Dent disease have been reported, of whom around 40 patients had Dent-2 disease, with various OCRL mutations described." (PMID 26108450, 2015). "We report a child with atypical Dent-2 disease, documented by an OCRL mutation, who presented with isolated proteinuria in the absence of any of the other classic criteria, particularly hypercalciuria." (PMID 26108450, 2015). "Two related disorders, oculocerebrorenal syndrome of Lowe (OCRL) and Dent-2 disease, are caused by mutation of the inositol 5-phosphatase OCRL1." (PMID 24499450, 2014). "OCRL was later identified as the second causative gene of Dent disease-2 (OMIM: 300555)." (PMID 40163114, 2025). "Around 50%–60% of patients carry pathogenic variants in the CLCN5 gene (Dent disease type 1 [DD1] Online Mendelian Inheritance in Man 300009), and 10%–15% of patients carry pathogenic variants in the OCRL gene (Dent disease type 2 Online Mendelian Inheritance in Man 300555)." (PMID 38814756, 2024).
Dent disease (continued). "Mutations in the CLCN5 and OCRL genes are known to cause Dent disease." (PMID 37799275, 2023). "Also, pathogenic OCRL variants leading to Dent’s disease have been reported in the context of kidney precipitate formation." (PMID 37597335, 2023). "DD caused by genetic changes in OCRL is known as Dent disease-2 (DD2) (OMIM #300555)." (PMID 38002082, 2023). "According to the results of the present study and others, it is speculated that mutations in the N-terminal domain of OCRL, where most Dent-2 disease mutations are located, would allow the expression of splicing variants that retain some biological activity." (PMID 35919034, 2022). "For example, a patient with OCRL mutations (Dent disease 2) was reported to receive immunosuppressive therapies including corticosteroids and cyclophosphamide, based on a misdiagnosis of nephrotic syndrome, before their inherited tubulopathy was correctly identified." (PMID 31935940, 2020). "Mutations in the OCRL gene also result in Dent disease type 2 (#300555)." (PMID 31676009, 2019). "CLCN5 variants were detected in 19 patients (Dent disease type 1, DD1), and OCRL variants were identified in 4 patients (Dent disease type 2, DD2)." (PMID 41361832, 2025). "In this aberrant splicing pattern, Met187 of OCRL was disrupted, indicating a milder phenotype, such as Dent disease-2." (PMID 40485688, 2025). "To date, Dent disease has been reported to be caused by more than 350 CLCN5 variants and 370 OCRL variants." (PMID 40420588, 2025). "Two-thirds of cases are associated with inactivating variants in the CLCN5 gene (Dent disease 1, DD1) and a few present variants in the OCRL gene (Dent disease 2, DD2)." (PMID 38002082, 2023). "A pathogenic variant in CLCN5 accounts for 60% of those with Dent disease (known as Dent disease-1, DD1) whereas a pathogenic variant in the OCRL gene accounts for another 15% (known as Dent disease-2, DD2)." (PMID 35549682, 2022). "It is caused by mutations in the chloride voltage-gated channel 5 (CLCN5) gene (Dent disease-1), or in the OCRL gene (Dent disease-2)." (PMID 35549682, 2022). "Renal clinical signs of Dent disease mainly reflect the expression of both ClC-5 and OCRL in the proximal tubular epithelial cells." (PMID 32860533, 2021). "The following year, using linkage analysis, the same group identified the OCRL gene, located in the Xq27–Xq27.1 region, as responsible for the Dent disease phenotype in 5 of their 13 cases." (PMID 32860533, 2021). "Dent disease is a rare X-linked tubulopathy caused by mutations either in CLCN5 (Dent disease type 1 (DD1) MIM #300009) or OCRL (Dent disease type 2 (DD2) MIM #300555) genes." (PMID 34680992, 2021). "The evidence to support most therapies in Dent disease is poor, which is reflected by highly variable treatment patterns in patients with CLCN5 and OCRL mutations." (PMID 32860533, 2021). "Dent disease (DD), an X-linked renal tubulopathy, is mainly caused by loss-of-function mutations in CLCN5 (DD1) and OCRL genes." (PMID 31947599, 2020). "A patient with Dent 2 disease was found to have mutations in both CLCN5 and OCRL genes, and an intermediary phenotype between DD and LS, while another case with OCRL and INPP5B variants presented with a Chiari I malformation." (PMID 32150856, 2020). "There are two forms of Dent disease, with the most common caused by mutations in the renal chloride transporter CLCN5 (Dent-1 disease) and the less common type caused by mutations in OCRL (Dent-2 disease)." (PMID 31811534, 2020). "Patients with a mutation in CLCN5 are classified as having Dent disease type 1 (Dent-1; MIM #300009), while patients with a mutation in OCRL are classified as Dent disease type 2 (Dent-2; MIM #300555)." (PMID 27757584, 2017). "We demonstrated that NP is a common finding in Dent disease both in patients with CLCN5 and OCRL mutations." (PMID 27757584, 2017).
Dent disease (continued). "As CLCN5 and OCRL mutations impair the function of the megalin–cubilin system, the loss of LMW proteins is an obligate finding in Dent disease." (PMID 27757584, 2017). "Recently, an atypical Dent’s disease phenotype was found to be due to co-inheritance of mutations in both CLCN5 and OCRL." (PMID 25019425, 2014). "Dent disease is a rare X-linked recessively inherited renal tubulopathy, caused by variants in the CLCN5 (Dent disease type 1, DD1) and OCRL (Dent disease type 2, DD2) genes, and characterized by low molecular weight proteinuria, hypercalciuria, microscopic hematuria, or nephrocalcinosis." (PMID 40420588, 2025). "UMOD, CLCN5, OCRL, NPHP4, and TTC21B may cause tubulointerstitial diseases such as ADTKD, NPHP, or Dent disease, but they are now included in the genetic panels for genetic screening of patients affected by FSGS, as they can phenocopy it." (PMID 37728640, 2024). "Moreover, the candidate genes PAK3, OCRL, DCX, PTK2, KCNQ3, SOX3, and LAMA1 were associated with autism, brain disease, Dent disease, and other conditions that present ID as a hallmark, corroborating our findings." (PMID 33922640, 2021). "While finding CLCN5 and OCRL mutations unquestionably leads to a diagnosis of Dent disease, it sheds no light on the disease’s phenotypic heterogeneity." (PMID 32860533, 2021). "Although mutations on the CLCN5 and OCRL genes are known to cause Dent disease, no such mutations are found in about 25–35% of cases, making diagnosis more challenging." (PMID 32860533, 2021). "Dent disease is a rare X-linked renal tubulopathy due to CLCN5 and OCRL (DD2) mutations." (PMID 34680992, 2021). "These include Dent disease (CLCN5, OCRL), AD tubulointerstitial kidney disease (ADTKD due to UMOD variants), nephronophthisis (TTC21B, NPHP4), Imerslund-Grasbeck syndrome 1 (CUBN) and papillorenal syndrome (PAX2)." (PMID 37578539, 2024). "The Renal proteinuria gene list corresponded to some genetic kidney diseases (CAKUT, tubulopathies, ciliopathies) that result in secondary FSGS such as Dent disease (CLCN5, OCRL), nephronophthisis (TTC21B, NPHP4), ADTKD-UMOD and Imerslund-Grasbeck syndrome 1 (CUBN)." (PMID 37578539, 2024). "They described 32 unrelated males with a Dent disease phenotype, 19 (about 60%) of them with a mutated CLCN5 gene (DD1), 5 (about 15%) with a mutated OCRL gene (DD2), and 8 (25%) with no mutations in either gene (DD3)." (PMID 32860533, 2021). "OCRL (Inositol Polyphosphate-5-Phosphatase) KO mice did not exhibit Lowe syndrome/Dent disease unless Inpp5b (Inositol Polyphosphate-5-Phosphatase B) was deleted in the proximal tubule as well." (PMID 32150856, 2020). "Approximately 50-60% of cases with Dent disease have CLCN5 mutations, 15-20% have OCRL mutations and the remaining cases have no detectable mutation." (PMID 29280738, 2017).
ciliopathy (8 papers, 2016 to 2024). A genetic disorder of the cellular cilia or the cilia anchoring structures, the basal bodies, or of ciliary function. "Mutations in OCRL could therefore cause its ciliopathy by an increase in PIP2, by overactivity of Rac1 and Cdc42, and by impaired endocytosis (impaired endocytosis may trigger ciliary shortening by causing agonist-induced vesicle budding)." (PMID 35079141, 2022). "Given the importance of PI signalling in ciliogenesis initiation identified here and the identification of various PI 5-phosphatases (such as INPP5E, INPP5B and OCRL) as causal loci for ciliopathies, we reason that PIPKIγ malfunction may also be correlated with ciliopathies." (PMID 26916822, 2016).
glaucoma (8 papers, 2013 to 2025). Increased pressure in the eyeball due to obstruction of the outflow of aqueous humor. "Zebrafish have been used to model various eye pathologies including cataracts and glaucoma, and it will be interesting to perform higher resolution imaging and functional analyses of the eye in the OCRL-deficient zebrafish models." (PMID 40778266, 2025). "Primary cilia are also important for maintaining healthy eye function, and it has been shown that OCRL-deficient mice are prone to glaucoma through disrupted cilia function." (PMID 40778266, 2025). "Evidence of the role of this enzyme in glaucoma pathogenesis derives from patients with mutations in OCRL who develop Lowe syndrome, a multisystem disease causing abnormalities in the brain, kidneys, and eyes." (PMID 35204770, 2022). "For example, the CRY-CIBN optogenetic system has been recently applied to animal models of glaucoma, suggesting a potential role of OCRL in the regulation of intraocular pressure in trabecular meshwork." (PMID 35204770, 2022). "We hypothesized that OCRL is expressed in human tissues that are responsible for cataract and glaucoma development." (PMID 23805271, 2013). "This study analyzes the intracellular localization and interactions of OCRL and INPP5B in ocular tissues responsible for cataract and glaucoma development." (PMID 23805271, 2013). "Taken together, OCRL and INPP5B are differentially expressed in the ocular tissues involved in glaucoma and cataract development." (PMID 23805271, 2013). "The roles of OCRL and INPP5B in the development of cataracts and glaucoma are not understood." (PMID 23805271, 2013).